RNF34 (ring finger protein 34)
Description:
E3 ubiquitin-protein ligase that regulates several biological processes through the ubiquitin-mediated proteasomal degradation of various target proteins. Ubiquitinates the caspases CASP8 and CASP10, promoting their proteasomal degradation, to negatively regulate cell death downstream of death domain receptors in the extrinsic pathway of apoptosis. May mediate 'Lys-48'-linked polyubiquitination of RIPK1 and its subsequent proteasomal degradation thereby indirectly regulating the tumor necrosis factor-mediated signaling pathway (Ref.13). Mediates PPARGC1A proteasomal degradation probably through ubiquitination thereby indirectly regulating the metabolism of brown fat cells. Possibly involved in innate immunity, through 'Lys-48'-linked polyubiquitination of NOD1 and its subsequent proteasomal degradation.
Synonyms: CARP-1; hRFI; RIFF; FLJ21786; RIF; CARP1; RFI
Tractability: Antibody: UniProt places it where antibodies can reach, with high confidence; its Gene Ontology location is reachable by antibodies, with high confidence. PROTAC: UniProt records ubiquitination sites on it; ubiquitination databases record sites on it; its protein half-life has been measured.
Gene: Protein-coding gene on chromosome 12 (121,400,078 to 121,430,623, forward strand). Ensembl gene ENSG00000170633.
Subcellular location: Cell membrane; Endomembrane system; Nucleus; Nucleus speckle; Cytoplasm, cytosol
Subcellular location (Human Protein Atlas): Nucleoplasm; Nuclear bodies; Nuclear speckles
Pathways (Reactome):
Immune System: Antigen processing: Ubiquitination & Proteasome degradation
Gene Ontology:
Molecular function: phosphatidylinositol phosphate binding; protein binding; ubiquitin protein ligase activity; ubiquitin protein ligase binding
Biological process: negative regulation of extrinsic apoptotic signaling pathway via death domain receptors; nucleotide-binding domain, leucine rich repeat containing receptor signaling pathway; proteasome-mediated ubiquitin-dependent protein catabolic process; protein K48-linked ubiquitination; protein ubiquitination; ubiquitin-dependent protein catabolic process; regulation of oxygen metabolic process; cellular response to cold
Cellular component: cytoplasm; nuclear body; nuclear speck; nucleoplasm; nucleus; plasma membrane; endomembrane system; cytosol
Genetic constraint (gnomAD): Loss-of-function variants: 9 observed, 32.83 expected, observed/expected ratio (o/e) 0.27, 90% interval 0.16 to 0.48. The upper end of that interval is the gene's LOEUF score, 0.48, which puts it in group 2 of 6, group 1 being the genes least tolerant of losing a copy. Missense variants: 319 observed, 451.65 expected, observed/expected ratio (o/e) 0.71, 90% interval 0.64 to 0.77. Synonymous variants: 139 observed, 172.12 expected, observed/expected ratio (o/e) 0.81, 90% interval 0.7 to 0.93.
Homologues: Orthologues: chimpanzee RNF34 (98% identical), macaque RNF34 (94% identical), pig RNF34 (91% identical), mouse Rnf34 (89% identical), dog RNF34 (87% identical), rat Rnf34 (87% identical), rabbit RNF34 (86% identical), guinea pig RNF34 (82% identical), tropical clawed frog rnf34 (70% identical), zebrafish rnf34a (63% identical), zebrafish rnf34b (61% identical), Drosophila melanogaster CG17019 (32% identical). Paralogues in human: RFFL (43% identical).
Diseases named in the same sentence as RNF34 in open-access papers:
RNF34 is named in the same sentence as 18 diseases in open-access papers, as found by Europe PMC text mining. Sharing a sentence is not in itself a finding about the gene and the disease. The quoted sentences say what the papers report.
viral infection (3 papers, 2020 to 2023). "Furthermore, the ubiquitination of MAVS by ring finger protein 34 (RNF34) causes NDP52-associated mitophagy to mitigate innate immune response upon viral infection." (PMID 32671064, 2020). "After viral infection activates RLR, RNF34 promotes the polyubiquitination of MAVS, which is then recognized by NDP52 and degraded by autophagy." (PMID 37442062, 2023). "During viral infection, the polyubiquitin translocation of MAVS induced by RNF34 (a cytosolic E3 ubiquitin ligase) could be recognized by NDP52 (ubiquitin receptor), resulting in the degradation of impaired mitochondria by autophagy." (PMID 35844503, 2022).
colorectal cancer (2 papers, 2017 to 2024). A primary or metastatic malignant neoplasm that affects the colon or rectum. "RNF34 has been identified previously to play a major role in colorectal cancer (CRC) carcinogenesis." (PMID 38410284, 2024).
brain edema (1 paper, 2019). Increased intracellular or extracellular fluid in brain tissue. "Our results showed that RNF34 overexpression in mice significantly aggravated the ICH-induced memory impairment, brain edema, infarction, hematoma volume, and loss of neuronal activity." (PMID 31704983, 2019).
Clear Cell Renal Cell Carcinoma (1 paper, 2024). "In clear cell renal cell carcinoma (ccRCC), however, the role and expression patterns of RNF34 are unknown." (PMID 38410284, 2024).
colorectal adenoma (1 paper, 2024). An adenoma that arises from the colon or rectum. "RNF34 is upregulated during carcinogenesis and tumor progression in the colorectal adenoma-carcinoma sequence and was already described to mediate chemoresistance." (PMID 38410284, 2024).
Dyskinesia (1 paper, 2019). A movement disorder which consists of effects including diminished voluntary movements and the presence of involuntary movements. "We provide the first evidence that RNF34 exacerbates oxidative stress, brain injury, and dyskinesia by reducing PGC-1α expression and potentiating mitochondrial dysfunction in the ICH mouse model." (PMID 31704983, 2019). "To explore whether the increased dyskinesia in RNF34 transgenic mice was the result of more severe brain injury, we examined brain edema, infarction, and neuronal activity." (PMID 31704983, 2019).
infarction (1 paper, 2019). A localised pathological necrosis of tissue resulting from obstruction of the blood supply usually by a thrombus, an embolus, or vascular torsion. "The results showed that RNF34 overexpression significantly increased brain edema and infarction, suggesting that RNF34 prevents recovery from the blood–brain barrier breakdown." (PMID 31704983, 2019).
memory impairment (1 paper, 2019). "More importantly, we found that RNF34 transgenic mice displayed more severe memory impairment after ICH surgery than wild-type mice, although RNF34 upregulation had no clear phenotype under normal physiological conditions." (PMID 31704983, 2019).
neuropathic pain (1 paper, 2025). Chronic pain caused by damage to nerve fibers. "Ring finger protein 34 (RNF34) gene increases in dorsal horn neurons of neuropathic pain rats and is suppressed following exercise." (PMID 40040749, 2025).
cancer (3 papers, 2022 to 2025). A tumor composed of atypical neoplastic, often pleomorphic cells that invade other tissues. "In accordance with these data, RNF34 mRNA overexpression was associated with unfavorable overall survival (OS), cancer-specific survival (CSS), and progression-free survival (PFS) in RCC as evaluated by Kaplan-Meier estimates and significant log-rank p-values (each log-rank p < 0.01)." (PMID 38410284, 2024). "In addition, RNF34 possesses the ability to hinder cancer cell apoptosis through the regulation of the NOD1 pathway." (PMID 38410284, 2024). "The antiapoptotic function brought RNF34 into the focus of cancer research." (PMID 38410284, 2024). "And RNF34 can also inhibit cancer cell apoptosis by regulating the NOD1 pathway." (PMID 35847032, 2022). "Interestingly, in CRC, RNF34 showed lower expression in advanced cancer stages." (PMID 38410284, 2024). "Belonging to the CARP family, RNF34 induces the ubiquitination and degradation of death effector domain (DED) caspase to suppress cancer cell apoptosis." (PMID 35847032, 2022).
tumor (1 paper, 2024). "Nuclear RNF34 expression was positively correlated with tumor grade (G1 vs. ≥ G2; p = 0.019) and showed a trend toward significance with positive lymph node status (p = 0.051)." (PMID 38410284, 2024). "Analyses of TCGA transcriptome data of RCC tissues showed that RNF34 mRNA is significantly overexpressed in RCC versus normal tissue adjacent to the tumor (NAT; p < 0.01)." (PMID 38410284, 2024). "Accordingly, patients with RNF34 expression in tumor tissue showed unfavorable clinical outcomes and poor survival." (PMID 38410284, 2024).
RNF34 also shares sentences with these, for which no sentence is quoted: hematoma (1 paper); infection (1); intracerebral hemorrhage (1); liver cancer (1); neurological diseases (1); renal cell carcinoma (1); SLE nephritis (1).